RANBP2 (RAN binding protein 2)
Diseases named in the same sentence as RANBP2 in open-access papers (continued):
Sharing a sentence is not in itself a finding about the gene and the disease.
infection (29 papers, 2010 to 2026). The state of being infected such as from the introduction of a foreign agent such as serum, vaccine, antigenic substance or organism. "Another plausible theory, which is the most widely accepted, is that mutations in RanBP2 directly trigger a “cytokine storm” after infection." (PMID 35408907, 2022). "By comparison, the dominantly inherited missense mutation in NUP358/RanBP2 leads to an infection-induced, acute, necrotizing encephalopathy." (PMID 33067781, 2021). "RanBP2 depletion caused an approximate 50% reduction in infection for most of the ape-derived viruses (HIV-1, SIVcpz, SIVgor)." (PMID 29518153, 2018). "RanBP2 mutation can also affect immune function by impairing the ability of mitochondria to regulate the secretion of proinflammatory cytokines, such as IL-1ß and IL-18, thereby altering the cellular response to infection." (PMID 40291183, 2025). "We next explored the requirements for RANBP2-Cyp for infection of other lentiviruses with distinct MX2 sensitivities from HIV-1." (PMID 39853118, 2025). "We also determined that the RANBP2-Cyp domain affects the requirements for other Nups for infection and MX2 sensitivity." (PMID 39853118, 2025). "We found that HIV-2 was more sensitive to depletion of RANBP2-Cyp than HIV-1 (~4.4-fold infection defect); however, MX2 sensitivity of HIV-2 was only slightly reduced in RANBP2∆Cyp cells." (PMID 39853118, 2025). "It has been reported that RanBP2 interacts with various viruses and affects either viral replication or infection through a variety of different mechanisms." (PMID 38203469, 2023). "Aside from the genetic influence of RANBP2 mutations, additional environmental factors, such as pathogen infection, are required for ANE1 development." (PMID 35408907, 2022). "For those who possess genetic variants of RANBP2, SCNIA, or HLADRB1*0901 contributing to infection-associated hyperinflammation, early administration of immunomodulation and/or hypothermia therapy is required." (PMID 36430629, 2022). "From all these data, an overall model emerges where upon infection, let-7 and RanBP2 modulate the inflammatory response by downregulating IL6, and potentially other cytokines." (PMID 33600493, 2021). "Here, RANBP2 exhibited a statistically significant fold-change (log) of -1.295 at 24 h post-infection, thus the role of RAMBP2-TRIM5α in coronavirus infection deserves further consideration." (PMID 32575076, 2020). "Recently, we have demonstrated that naturally occurring evolutionary differences between primate species in a nuclear pore component called RanBP2/Nup358 alter infection by simian immunodeficiency viruses (SIVs)." (PMID 29694349, 2018). "In agreement with previous reports, we found that RANBP2 knockdown inhibited HIV-1WT infection of HeLa cells." (PMID 30084827, 2018). "RANBP2 depletion also eliminated the modest (three-fold) reduction in HIV-1WT infection of CsA-treated HT1080 cells." (PMID 30084827, 2018). "Conversely, the enhancing effects of CsA addition on HIV-1A92E infectivity in HeLa cells, and the profound inhibitory effect of CsA on HIV-1N57S infection in HT1080 cells were maintained when RANBP2 was depleted." (PMID 30084827, 2018). "Similar results were obtained if rhTRIM5α was transfected prior to RanBP2 knockdown, and at all tested multiplicities of infection (MOI)." (PMID 30456314, 2018). "It was recently reported that the Kinesin-1 motor, KIF5B, relocalizes RanBP2 to the cytoplasm during infection." (PMID 29518153, 2018). "This initial scan showed robust effects on infection efficiency for the nuclear import factors Transportin-3 and RanBP2, confirming observations from earlier studies; therefore, these genes were studied in detail as described in the following sections." (PMID 21423673, 2011). "Furthermore, HIV-1 CA mutant viruses G89V and P90A, which are impaired for CypA binding, exhibit reduced dependence on RANBP2 for infection." (PMID 39853118, 2025).
infection (continued). "SIV from tantalus monkeys (SIVagmTAN) also binds Cyps (53, –, 55), but it is unknown whether it requires RANBP2 for infection." (PMID 39853118, 2025). "To better understand the consequences of altered pIIIa import on subsequent stages of virus replication, we performed purification of virus from RANBP2-siRNA, and NC-siRNA treated cells at five days post infection (MOI of 0.1), and separated viral bands by CsCl-density gradient ultracentrifugation." (PMID 35709296, 2022). "USP9x and RANBP2 immunoprecipitations in HAdV-C5 infection each pulled down pIIIa." (PMID 35709296, 2022). "Moreover, while HIV-1G89V infection was slightly increased by MX2 in unmanipulated HT1080 cells, RANBP2 depletion caused HIV-1G89V to be inhibited by MX2." (PMID 30084827, 2018). "Furthermore, we found that, unlike HIV CA, SIV CA did not require a direct interaction with the Cyp-like domain of Nup358/RanBP2 to carry out successful infection." (PMID 23883001, 2013). "However, CA-RANBP2-Cyp interactions may be involved in infection of cells derived from the natural host species of these viruses, especially given that the RANBP2-Cyp domain exhibits evidence of evolution under positive selection." (PMID 39853118, 2025). "THP89 cell line is thus an ideal system to study whether RanBP2 is directly involved in the nuclear export of viral mRNAs and is superior to transfection and infection experiments wherein viral DNA nuclear import and integration are additional steps to be suspected before concluding Rev function." (PMID 21179483, 2010). "There were, however, a number of differences in Nup requirements for HIV-1WT infection in RANBP2∆Cyp cells, including a dramatic increase in sensitivity to NUP155 knockdown, and decreased sensitivity to NUP107, NUP93, and RANBP2 depletion." (PMID 39853118, 2025). "We observed a modest though significant reduction in HIV-1WT infection (~2.3-fold) as well as a reduction in MX2 sensitivity in RANBP2∆Cyp cells, suggesting that in addition to CypA, CA-RANBP2-Cyp interactions affect MX2 activity against HIV-1." (PMID 39853118, 2025). "Interestingly, while deletion of RANBP2-Cyp had marginal effects on infection by HIV-1G89V CA as expected, the ability of MX2 to enhance infection of this mutant was reduced in RANBP2∆Cyp cells, suggesting there may also be CA-independent effects of the Cyp domain on MX2 activity." (PMID 39853118, 2025). "Further IFN and antiviral related proteins were upregulated upon infection with PeV-A3 (EIF2AK2, STAT1), or PeV-A1 (NCAM1, POM121), and downregulated upon PeV-A1 infection (EIF4G1, UBE2N, RANBP2, FLNA)." (PMID 38514653, 2024). "We also demonstrated that RanBP2 facilitates both DNA virus (HSV-1) and RNA virus (VSV) infection, by suppressing interferon-α-mediated antiviral signaling likely via its SUMO E3 ligase activity." (PMID 38203469, 2023). "For example, RanBP2/Nup358-dependent SUMOylation of TRIM5-alpha activates its ability to uncoat viruses and promote abortive infection." (PMID 35485383, 2022). "However, other cellular processes, such as mitochondrial functioning, may also be directly impacted by RanBP2 and may be particularly important to elucidate given similarities with some mitochondrial disorders in which neurologic injury is triggered by infection." (PMID 35058867, 2021). "Notably, 9 nucleoporins (NUP58, NUP214, NUP98, NUP54, NUP62, NUP88, NUP153, POM121/NUP121 and RANBP2/NUP358) and the mRNA export factor Rae1 were present in both the CebN infection and transfection interactomes." (PMID 38712050, 2024). "Here, we observed that VSV-GFP infection was significantly attenuated in RanBP2-dE3-1 cells compared to unmodified cells even without exogenous IFN-α treatment." (PMID 38203469, 2023). "We observed that VSV-GFP infection was significantly inhibited in RanBP2-dE3-1 cells compared to Ctrl cells even without exogenous IFN-α treatment." (PMID 38203469, 2023).
infection (continued). "Consistent with what we observed with HSV-1, exogenous IFN-α stimulation still suppressed VSV-GFP infection in both Ctrl and RanBP2-dE3-1 cells, and the efficiency of VSV-GFP infection was significantly lower in RanBP2-dE3-1 cells compared to Ctrl cells after exogenous IFN-α stimulation." (PMID 38203469, 2023). "RanBP2 depletion does not alter infection with SIVmac (macaques), SIVmus (mustached monkeys), SIVmon (mona monkeys), or SIVcol (colobus guereza monkeys)." (PMID 29518153, 2018). "We observed that infection by CA mutants restricted by CPSF6 is less dependent or independent of the nucleoporins RanBP2 and Nup153." (PMID 24415937, 2014). "Because Nesprin-2 and RanBP2 are both cytoplasmic-facing nuclear membrane proteins that bind to the BICD2-dynein motor complex, we hypothesized that one (or both) of these host factors may be responsible for capturing SV40 to facilitate nuclear entry and infection." (PMID 36067270, 2022). "Given this, it is likely that SUMOylation of TRIM5α by RanBP2 can both promote and inhibit (via nuclear sequestration) its activity as a retroviral restriction factor, and that this is fine-tuned according to the cell type (lymphocytes versus DC13) and whether the cell is undergoing infection." (PMID 30456314, 2018). "The results showed that post-infection, SUMO2/3 partially co-localized with LaminB1, but not with RanGAP1 and RanBP2." (PMID 40521184, 2025). "Deletion of the RANBP2-Cyp domain did not result in global changes to HIV-1WT sensitivity to Nup depletion, as most Nup and NTR depletions had similar effects on HIV-1WT infection in both RANBP2WT and RANBP2∆Cyp cells." (PMID 39853118, 2025). "Therefore, while in vitro experiments indicate that additional domains of RANBP2 can interact with the HIV CA, our data suggest that these interactions are not required for infection, at least in HT1080 cells." (PMID 39853118, 2025). "Indeed, with the notable exceptions of RANBP2 and NUP153, Nup depletions generally had a smaller effect on HIV-1WT infection in non-dividing as compared to dividing HeLa cells." (PMID 30084827, 2018).
cancer (27 papers, 2011 to 2025). A tumor composed of atypical neoplastic, often pleomorphic cells that invade other tissues. "Mutation or dysregulation of RANBP2 can lead to the development of a range of human pathologies, including these neurodegenerative diseases, as well as cancer." (PMID 41465490, 2025). "The Ranbp2 protein relates to cancer cells, and genetic point mutations and translocations are associated with tumorigenesis." (PMID 34635181, 2021). "For example, although it is known from previous studies that RANBP2, as a SUMO E3 ligase, has been implicated in the development of a variety of cancers, the existence of corresponding inhibitors of RANBP2 that can inhibit its role as an E3 ligase remains a mystery." (PMID 40271196, 2025). "Both RAN and RANBP2 are involved in mitosis and are associated with a variety of cancers." (PMID 31949483, 2020). "RAN/RANBP2 genes are reported to be associated with cancer development." (PMID 29706609, 2018). "This is essential due to the observed lack of correlation between the chemical sensitivity of amrubicin, a fully synthetic anthracycline anti-cancer agent and effective TopoII inhibitor, and the mRNA expression levels of RANBP2, TopoII-α, and TopoII-β genes." (PMID 40271196, 2025). "Post-treatment cold tumors also acquired more cancer-specific mutations (i.e., BRCA2, TPR, OMD, RANBP2, EP300)." (PMID 38714665, 2024). "Interaction of insulin-like growth factor-1 receptor (IGF1R) with Ranbp2 is essential for IGF1R sumoylation that plays a crucial role in cancer cell progression." (PMID 34635181, 2021). "The RANBP2-mediated RAN GTPase regulation has been implicated in the initiation and progression of several cancers." (PMID 33816306, 2021). "Additionally, it delves into exploring RANBP2 as a prospective therapeutic target for cancer treatment, offering insights into the avenues that scholars should pursue in their subsequent research endeavors." (PMID 40271196, 2025). "Therefore, we might speculate that the mechanism through which SAHA leads to a reduction in HDAC4 is through RANBP2-mediated proteasome degradation as determined for cancer cell lines." (PMID 22140466, 2011). "Apart from RANBP2, multiple SUMO enzymes are responsible for cancer progression and represent targetable cancer metabolic biomarkers." (PMID 34298689, 2021). "We previously found an unexpected role of NUP358/Ran-binding protein 2 showing that, in addition to its primary function as a structural component of NPC in cancer cells division, it is also involved in mitotic catastrophe in HeLa cells." (PMID 29568361, 2018). "Besides PIASs, additional ligases, such as RanBP2 and CBX4, are key to cancer, the latter being involved in a variety of cancer types." (PMID 35887358, 2022). "Furthermore, it has been shown that in cancer cell lines, SAHA can lead to the degradation of class IIa HDACs 4 and 5 via RANBP2 mediated proteasome degradation in vitro." (PMID 22140466, 2011).
neurological disease (5 papers, 2012 to 2024). "The cytosolic and peripheral nucleoporin Ranbp2 is a crucial regulator of the Ran GTPase cycle and of the proteostasis of neurological disease-prone substrates, but the roles of Ranbp2 in motoneuron biology and disease remain unknown." (PMID 28100513, 2017). "First, we examined markers for different compartments of the NPC which have been shown to been altered in neurologic diseases, including Nup62 and Nup98 in the central channel, POM121 to demarcate the transmembrane ring, and RanBP2 within the cytoplasmic ring and filaments." (PMID 39452051, 2024).
neurodegenerative disease (4 papers, 2006 to 2025). A disorder of the central nervous system characterized by gradual and progressive loss of neural tissue and neurologic function. "Collectively, these and other data point toward a number of RanBP2-mediated metabolic and neurodegenerative diseases of acute and insidious clinical expressions sharing strong gene-environment interactions and broader spectra of metabolic footprints and pathomechanisms than hitherto realized." (PMID 22821000, 2012).
RANBP2 also shares sentences with these, for which no sentence is quoted: acute myeloid leukemia (4 papers); amyotrophic lateral sclerosis (2); anaplastic large cell lymphoma (2); Huntington disease (2); lung adenocarcinoma (2); acute disseminated encephalomyelitis (1); Acute encephalopathy (1); acute hemorrhagic encephalitis (1); acute transverse myelitis (1); Akinesia (1); Alzheimer disease (1); anaemia (1); astrocytoma (1); B-cell lymphoma (1); breast tumor (1); cobblestone lissencephaly (1); diabetic retinopathy (1); endometrial cancer (1); Glucose intolerance (1); glycine encephalopathy (1); heart failure (1); hematopoietic neoplasms (1); Hepatitis (1); Histiocytosis (1); holoprosencephaly (1); Insulin resistance (1); intrahepatic cholestasis (1); Leigh’s disease (1); leukemia (1); lymphoid neoplasm (1).
A further 18 diseases each share a sentence with RANBP2 in 1 paper.